CACNA1C (calcium voltage-gated channel subunit alpha1 C)
Diseases named in the same sentence as CACNA1C in open-access papers (continued):
Sharing a sentence is not in itself a finding about the gene and the disease.
depression (70 papers, 2013 to 2025). "The neuropsychiatric disorder risk gene CACNA1C is closely related to depression, its abnormal expression disrupts Ca2+ homeostasis, leads to abnormal brain development, and increases anxiety." (PMID 39170573, 2024). "Genome-wide association studies (GWAS) have identified Cacna1c as a candidate risk gene for multiple neuropsychiatric disorders, including bipolar disorder, schizophrenia and depression." (PMID 37189442, 2023). "The role of calcium in the pathophysiology of bipolar (BP) disorders and depression has been studied, and some of the calcium-related genes, such as CACNA1C, have been reported to be associated with the development of BP illness and depression." (PMID 33515455, 2021). "CACNA1C polymorphisms associated with depression have also been linked to increased Cav1.2 mRNA and l-type calcium currents in induced neurons obtained from skin fibroblasts of patients with depressive-like behaviors." (PMID 33291797, 2020). "Evidence from animal studies, clinical studies, and genome-wide association studies supports the findings that CACNA1C is closely associated with depression." (PMID 32161558, 2020). "Genome-wide association studies (GWAS) exhibit a strong link between Rs1006737 polymorphisms in the CACNA1C gene (that encodes for the Cav1.2 calcium channel) and the development of mood disorders such as bipolar disorder and major depression." (PMID 33291797, 2020). "Studies on the interaction between CACNA1C polymorphism, threatening life events, and depression included in the meta-analysis." (PMID 32038325, 2019). "Several reports also provided strong association between CACNA1C, a potential target gene of miR-137, with the risk of major depression." (PMID 31736707, 2019). "CACNA1C rs1006737 is a novel variant in discovery of replicable associations in major depressive disorder (MDD)." (PMID 32038325, 2019). "It was found that highly variable probes in depression-discordant MZ pairs were located in genes within enriched biological pathways and previously associated with depression, such as CACNA1C, IGF2 and MAPK11." (PMID 25918994, 2015). "For example, there is evidence that rs100637 (a SCZ-associated SNP, located in intron 3 of the CACNA1C gene) is associated with major depressive disorder (MDD), SCZ and attention deficit hyperactivity disorder, leads to changes in CACNA1C expression in both human carriers and induced human neurons." (PMID 33057948, 2021). "Finally, through further mediation analyses, we found that the relationship between the CACNA1C rs11832738 polymorphism and depression severity was mediated by the altered spontaneous activity of MFG_R." (PMID 32161558, 2020). "A genetic variant in CACNA1C rs11832738 may influence depression severity in MDD patients by moderating spontaneous MFG_R activity." (PMID 32161558, 2020). "In addition, several reports have provided strong association between CACNA1C, a potential target gene of miR-137, with the risk of major depression." (PMID 31736707, 2019). "Considering the heterogeneity of MDD, our data raises the possibility that SNPs in CACNA1C might predict the risk for depression mainly in individuals with a history of trauma or severe stress." (PMID 28696432, 2018). "We hypothesized that CACNA1C polymorphisms may affect the cognitive recovery after 6 weeks of treatment for major depression in bipolar patients." (PMID 28765577, 2017). "CACNA1C is a risk gene common to bipolar, schizophrenic and major depressive disorders." (PMID 25566074, 2014). "In addition to CACNA1C, we found several DMRs in Pcdh9, another susceptibility gene for depression, further highlighting that the shared pathways between prenatal stressors may reprogram key biological systems involved in mental health." (PMID 34828381, 2021). "Some studies have implicated a large number of genes associated with depression, including HTR2A, CACNA1C, BDNF, CRHR1, GSK3β, TPH1, among others, as detailed in a systematic review." (PMID 38075264, 2023).
depression (continued). "Eight SNPs were identified as associated with depressive disorder and belonged to the ANK3, BDNF, CACNA1C, and GRID1 genotypes, with the majority belonging to the ANK3 and CACNA1C genotypes." (PMID 38012695, 2023). "Many recent reports have been published on the association between CACNA1C SNPs and behavior, neurogenesis, and risk of psychiatric disorders such as SCZ, BD, and depression." (PMID 36193501, 2022). "Specifically, there was an association between the SZ CACNA1C PES and increased odds of depression, while the SZ RPS17 network PES was associated with increased odds of self-reported OCD." (PMID 36055211, 2022). "After linkage disequilibrium-pruning based on r2-values of 0.2, 32 of the 465 tested SNPs in the CACNA1C locus showed nominal significant interactions with adult trauma exposure on Beck Depression Inventory scores." (PMID 28696432, 2018). "Our data suggest the involvement of CACNA1C SNP rs10466907 in cognitive recovery during the treatment of depression and an effect of rs5861995 on cognitive impairment during major depression." (PMID 28765577, 2017). "Similarly, the rs1990322 locus in CACNA1C at cg24393317 was significantly associated with PTSD and variable methylation was found between depression-discordant monozygotic twins at position cg10031793 in CACNA1C." (PMID 36803254, 2023). "This is recapitulated in humans through the interaction of CACNA1C SNPs with adverse life events to later alter the risk of developing symptoms of a neuropsychiatric disorder, seen specifically in the interaction of CACNA1C and adult trauma to predict depression symptoms in humans." (PMID 36803254, 2023). "Moreover, for CACNA1C G allele carriers, the ALFF of MFG_R was significantly positively correlated with depression severity." (PMID 32161558, 2020). "Our results suggest that rs11832738 might contribute to depression severity through altered CACNA1C gene expression; however, this requires further research." (PMID 32161558, 2020). "Our data suggest that the tested CACNA1C SNPs may have impacts on cognitive recovery from depression." (PMID 28765577, 2017). "Therefore, we hypothesize that DNA methylation and Cacna1C may jointly play a role in the process of depression." (PMID 39268349, 2024). "Furthermore, pathways including the CACNA1C, a Calcium channel-related gene, could be involved in treatment-resistant depression, which could be considered for developing multi-marker predictors." (PMID 37559539, 2023). "Eight SNPs were associated with depressive disorder, namely rs142101917, rs191244436, and rs541490076 of the ANK3 genotype; rs193069165 of the BDNF genotype; rs116938681, rs188470158, and rs565998563 of the CACNA1C genotype; and rs558147168 of the GRID1 genotype." (PMID 38012695, 2023). "Previous studies have suggested that the CACNA1C SNP can alter the function of the frontal cortex and that the knockdown of CACNA1C in the frontal cortex has an antidepressant-like effect, suggesting that CACNA1C might affect depression by altering frontal lobe function." (PMID 32161558, 2020). "It is not known whether exposure to cannabis or cannabis-derived compounds restores the DNAm and expression levels of CACNA1C to those of non-carriers or whether the restoration is associated with an improvement in depression symptoms; these questions need further investigation." (PMID 36011346, 2022). "Animal studies have confirmed the involvement of CACNA1C in the pathophysiolgy of depression: Following CUMS, Cav1.2 levels were found to be increased in the PFC." (PMID 34858192, 2021). "According to the generalized estimating equation analysis results, 8 single nucleotide polymorphisms (SNPs) belonging to the ANK3, BDNF, CACNA1C, and GRID1 genotypes were significantly correlated with depressive disorder (P < .001), with the majority belonging to the ANK3 and CACNA1C." (PMID 38012695, 2023).
depression (continued). "Other studies that investigated DNA methylation signatures of depression in discordant monozygotic twins study design implicated epigenetic changes in VDR26, HOXB7, CACNA1C, STK32C, NR1C3, and MYC genes among others, but not in KLK8 or DAZAP247,108,117,118." (PMID 31477683, 2019).
Arrhythmia (61 papers, 2014 to 2026). Any cardiac rhythm other than the normal sinus rhythm. "SCN5A regulates the influx of Na+ while CACNA1C encodes a voltage-gated Ca2+ channel that mediates Ca2+ entry during the cardiac action potential and is implicated in arrhythmia when mutated." (PMID 41369369, 2025). "We illustrate the resulting inference using the predictions of two broadly expressed disease genes: CACNA1C that underlies arrhythmia, affecting the heart, and DMD that underlies Duchenne muscular dystrophy, affecting skeletal muscle." (PMID 37232043, 2023). "Secondly, the expression profile and function of CACNA1C gene encoding Cav1.2 proteins, and its gain-of-function mutation in TS leading to multiple organ disease phenotypes especially arrhythmia are discussed." (PMID 37132248, 2023). "CACNA1C variants can lead to several conditions including Timothy syndrome which is characterized by neurodevelopmental problems, cardiac arrhythmias, and craniofacial deformities." (PMID 37448958, 2023). "Patients carrying the CACNA1C rs2283274-C allele showed significant QT prolongations, which are best known to predispose to life-threatening cardiac arrhythmias such as Torsade de Pointes." (PMID 36421807, 2022). "In conclusion, altered ICaL due to the CACNA1C R858H mutation increases arrhythmia risk due to afterdepolarizations and increased tissue vulnerability to unidirectional conduction block." (PMID 29046645, 2017). "In this study, we identified a novel mechanism of VT resulted from enhanced repolarization dispersion which is a key factor for arrhythmias in the CACNA1C G1911R mutation using multi-scale computational models of the human ventricle." (PMID 27502440, 2016). "Among all combinations between the 19 phenotypes and 34 SNPs, the strongest association was observed between rs4765913 in the CACNA1C gene and the phenotype ‘cardiac dysrhythmias'." (PMID 27529678, 2016). "In fact, rs216013 is the only CACNA1C SNP in the PheWAS catalog results, and the catalog reports nominally significant evidence for association of this SNP with cardiac dysrhythmias (P=0.034)." (PMID 27529678, 2016). "One finding of potential interest is the association between CACNA1C genetic variation and the ‘cardiac dysrhythmias' phenotype." (PMID 27529678, 2016). "Screening of arrhythmia associated genes revealed a G1911R variant in the CACNA1C-encoded L-type calcium channel α1C subunit." (PMID 25184293, 2014). "Because these proteins also control cardiac electrophysiology, variants in their encoding genes (KCNH2, CACNA1C) may increase arrhythmia and SCD risk." (PMID 37005595, 2023). "The reduced expression of CACNA1C/Cav1.2 (ICa,L) has been shown to be associated with heart diseases, including atrial fibrillation, ventricular tachycardia, and dilated cardiomyopathy, contributing to the pathogenesis of arrhythmia." (PMID 31912231, 2020). "Isolated cardiac arrhythmia due to a variant in CACNA1C is of recent knowledge." (PMID 30345660, 2019). "Although the CACNA1C mutations were well identified in patients with cardiac arrhythmias, mechanisms by which cardiac arrhythmias are generated in such genetic mutation conditions remain unclear." (PMID 27502440, 2016). "In this context, the identification of a SUID case in which this variant was present may provide additional support for our hypothesis that p.G1911R in CACNA1C increases arrhythmia susceptibility." (PMID 25184293, 2014). "We identified a variant in CACNA1C in a male child of Filipino descent with arrhythmias and extracardiac features by candidate gene sequencing and performed functional expression studies to electrophysiologically characterize the effects of the variant on CaV1.2 channels." (PMID 25184293, 2014). "These analyses expand our understanding of how variants in CACNA1C can lead to an arrhythmogenic phenotype and suggest that rs374528680 encoding p.G1911R in CaV1.2 may increase arrhythmia susceptibility under certain conditions." (PMID 25184293, 2014).
Arrhythmia (continued). "In the context of the recently reported p.R1906Q variant in a patient with LQTS, this C-terminal region may become known as a new hotspot for arrhythmia-causing variants in CACNA1C." (PMID 25184293, 2014). "miR-155 might directly influence arrhythmia outcomes by targeting critical ion channel gene expression, including CACNA1C and KCNA4, which encode the cardiac L-type Ca2+ channel (ICaL) α1c and the initial component of the transient outward potassium current (Ito1), respectively." (PMID 26319023, 2015). "Our top candidates included previously known modifier genes (FHOD3), a gene known to cause DCM and HCM when mutated (TTN) and genes associated with related cardiovascular phenotypes such as heart failure (HNRNPC) and arrhythmia (CACNA1C, RYR2)." (PMID 40791945, 2025). "Strong association was observed between the rs476593 section on the CACNA1C gene and the phenotype of cardiac dysrhythmias." (PMID 41141090, 2025). "In case of the arrhythmia gene CACNA1C, that process was “membrane depolarization during atrial cardiac muscle cell action potential,” in accordance with arrhythmia phenotypes." (PMID 37232043, 2023). "The major genes responsible for such inherited arrhythmias are RYR2 (encoding for RYR2), CASQ2 (encoding for calsequestrin-2), and CACNA1C (encoding for CaV1.2)." (PMID 31426283, 2019). "Variants in two ion channel genes (CACNA1C and KCNQ1) have been identified in patients with mixed HCM and arrhythmia phenotypes but are suggested to be responsible for the arrhythmic rather than hypertrophic component of the phenotype in these cases." (PMID 28082330, 2017). "Clinically, CACNA1C is a target for the treatment of hypertension and arrhythmia." (PMID 39790063, 2025). "There is an incredible amount of phenotypic variability among individuals bearing variants in the CACNA1C gene and TS no longer exclusively applies to children with both cardiac arrhythmias and syndactyly." (PMID 34079780, 2021). "Mutations in LTCC genes, including CACNA1C, CACNA1D, CACNB2 and CACNA2D, will induce the dysfunctions of calcium channels, which result in the abnormal excitations of cardiomyocytes, and finally lead to cardiac arrhythmias." (PMID 30027834, 2018). "The CACNA1C-Q1916R variant was not considered to be "pathogenic", although it has been found in two small Japanese cohorts with inherited arrhythmias associated with sudden death." (PMID 28493952, 2017). "The CACNA1C SNP with suggestive evidence of association with ‘cardiac dysrhythmias' in our study (rs4765913) was not included in the analyses performed by the eMERGE network that are documented in the PheWAS catalog." (PMID 27529678, 2016). "Although it is important to make clear the limitations of the models in this study, they do not alter our conclusion on that the CACNA1C G1911R mutation promotes initiation and maintenance of cardiac arrhythmias." (PMID 27502440, 2016). "Male, but not female, CIH rats have altered expression of Cav3, Cacna1c, Cacnb2, Kcne5, Kcnd2, and Hcn2 which may preferentially predispose postnatal males to develop arrhythmia." (PMID 38981849, 2024). "The top association findings suggested that the BD risk alleles at SNP rs4765913 in CACNA1C gene and rs7042161 in SVEP1 may be associated with increased risk of ‘cardiac dysrhythmias' (odds ratio (OR)=1.1, P=3.4 × 10−3) and ‘essential hypertension' (OR=1.1, P=3.5 × 10−3), respectively." (PMID 27529678, 2016). "Because this SNP is in very low linkage disequilibrium with rs4765913 (r2=0.012), the potential association of rs216013 with cardiac dysrhythmias does not constitute replication of the result in the MayoGC sample, but it may provide additional evidence for a role of CACNA1C in this phenotype." (PMID 27529678, 2016).
Arrhythmia (continued). "Also, they determined that there is diurnal variation in percentage of myocytes that develop arrhythmias in response to β-adrenergic stimulation, yet without changes in relevant gene transcription: L-type Ca2+ channel (cacna1c) or β1-adrenoreceptor." (PMID 27459195, 2016).